NQO1 (NAD(P)H quinone dehydrogenase 1)
Diseases named in the same sentence as NQO1 in open-access papers (continued):
Sharing a sentence is not in itself a finding about the gene and the disease.
cancer (continued). "This naphthoquinone is now under investigation for the treatment of specific cancers associated with elevated NQO1 levels, such as breast, non-small cell lung, pancreatic, colon, and prostate cancers, and is currently in phase II clinical trials for the treatment of pancreatic cancer." (PMID 19924086, 2009). "β-Lapachone (LAP), an FDA-approved small molecule, targets NAD(P)H: quinone oxidoreductase-1 (NQO1), which overexpressed in cancer cells (5–200 × higher than in normal tissues)." (PMID 41496203, 2026). "NRF2-induced antioxidant genes, such as NQO1, HO-1, and GCLC, help mitigate oxidative stress, which is often elevated in cancer-prone tissues." (PMID 41333220, 2025). "NQO1 is an antioxidant enzyme regulated by the transcription factor NRF2, exhibiting elevated activity under the conditions typical of human malignant tumors." (PMID 40710294, 2025). "β-Lap is a naturally occurring quinone compound derived from the bark of the Lapacho tree that is activated by the enzyme NAD(P)H:quinone oxidoreductase (NQO1), which is often overexpressed in cancer cells." (PMID 40227824, 2025). "The expressions of NRF2 target gene Nqo1 and Gsta4 were also downregulated in the DKO 3LL cell line, demonstrating successful reversal of NRF2 hyperactivation in the KEAP1-KO cancer cells." (PMID 41035689, 2025). "One downregulated protein, matrix metalloproteinase-9 (MMP9), and two upregulated proteins (NADPH: quinone oxidoreductase-1 (NQO1) and Sodium/potassium ATPase (Na+/K+-ATPase)) were correlated with a suppression in the proliferation and migration of cancer." (PMID 38732643, 2024). "The Nrf2/NADPH: Quinone Oxidoreductase 1 (NQO1) signaling pathway plays a key role in the development and progression of many diseases, including cancer, retinal aging, and others." (PMID 38892389, 2024). "Upon internalization by NQO1-proficient cells, the prodrug released fluorescent CPT and elicited a potent cytotoxicity (IC50 of 0.71 μM) against cancer cells." (PMID 39120303, 2024). "The NRF2/KEAP1 signaling pathway regulates NQO1 during OIS, and its depletion delays senescence onset, facilitating cancer progression." (PMID 39538363, 2024). "When they directed this probe to the mitochondria in cancer cells, the AIE dye was released by NQO1 catalysis, which subsequently formed aggregates and perturbed the mitochondrial metabolism, leading to cell death." (PMID 39120303, 2024). "Based on the overexpression of NAD(P)H:quinone oxidoreductase-1 (NQO1) and the biotin receptor in cancer cells, compound 35 was designed by the introduction of both biotin and quinone propionic acid into SN38 at C-10 position." (PMID 37446591, 2023). "Following Ru-bdcurc treatment, cancer cells greatly increased the NRF2 protein levels and the expression of NRF2 targets, including HO-1, NQO1, and p62/SQSTM1, suggesting the induction of NRF2 transcriptional activity." (PMID 36831129, 2023). "Because the main mechanism of action by NQO1-activatable drugs is the generation of superoxide and H2O2, the ability for a cancer cell to manage these oxidants is a critical metric for chemotherapeutic response." (PMID 36978989, 2023). "In NQO1-expressing cells, sic-Fos transfection increased radiosensitivity, whereas overexpression of CKS1 in sic-Fos-transfected cancer cells led to recovery of radioresistance." (PMID 36793872, 2023). "Although both NQO1 and CKS1 are overexpressed in cancer, the potential interactions between the two proteins and their effects on the cell cycle have yet to be established." (PMID 36793872, 2023). "Knockdown of NQO1 induced an increase in DSBs, thereby markedly increasing HR, decreasing NHEJ, and enhancing the radiosensitivity of cancer cells." (PMID 36793872, 2023).
cancer (continued). "Commercially available benzo[e]perimidine-4-carboxylic acid 3a displays the greatest similarity in anti-cancer activity to DPIQ, with a PCC of 0.87, and a moderate to strong PCC of 0.64 to NQO1 expression across the NCI-60 cell line panel." (PMID 37446864, 2023). "We assessed 19,221 genes and observed a positive correlation between FIN sensitivity and the expression of several well-known NRF2 targets, including NQO1, SLC7A11, GPX2, GCLC, and FTH1, across various cancer cell lines at both the mRNA and protein levels." (PMID 37633973, 2023). "The correlations between NQO1 and CKS1 expression and clinicopathological features in cancer patients were determined with the aid of publicly available data sets and immunohistochemical analysis." (PMID 36793872, 2023). "Consistent with this, high NQO1 expression was correlated with increased CKS1 and poor prognosis in cancer patients." (PMID 36793872, 2023). "High-level expression of NQO1 is consistently correlated with elevated expression of CKS1 and poor survival in cancer patients." (PMID 36793872, 2023). "In addition, radiological models of the whole tumor and peritumoral areas obtained using CT radiomics technology from The Cancer Genome Atlas (TCGA) and The Cancer Imaging Archive (TCIA) were first introduced to evaluate whether the radiomics model could noninvasively predict NQO1 expression levels." (PMID 37695786, 2023). "The early 1960s witnessed the discovery of DT-diaphorase (later renamed NQO1) by Ernster and team, leading to extensive studies on its role in various cancers." (PMID 38136388, 2023). "Taken together, our results suggest that NQO1 regulates CKS1B mRNA transcription and cell cycle progression at the G2/M phase in cancer cells through induction of c-Fos expression." (PMID 36793872, 2023). "The expressions of GLS and NQO1 were significantly higher in TCGA and ICGC cancer tissues, while IYD expression was significantly lower in HCC tissues compared with normal tissues." (PMID 36582227, 2022). "Besides, drug resistance may also be a result of the inactivation of drugs caused by detoxifying enzymes expressed in cancer cells, such asase I enzymes- NAD(P)H-quinone oxidoreductase 1 (NQO1), and phase II enzymes-placental (P) isoform of glutathione-S-transferase (GSTP1)." (PMID 35372014, 2022). "We evaluated metabolic turnover in MDA-MB-231 NQO1+, MDA-MB-231 NQO1−, MDA-MB-468, and T47D cancer cells by measuring the isotopic labeling of metabolites from a [U-13C]glucose tracer." (PMID 35893874, 2022). "Moreover, NQs are the substrate of the enzyme NAD(P)H quinone oxidoreductase 1 (NQO1), which activates quinone-like compounds through reduction, is involved in redox process, and, being often overexpressed in cancer tissues, can serve as a target for cancer therapy." (PMID 35956896, 2022). "It was found that cytotoxic activity of the studied hybrids was increasing against the cell lines with higher NQO1 protein level, such as breast (MCF-7 and T47D) and lung (A549) cancers." (PMID 36234741, 2022). "nAD(P)H-quinone oxidoreductase 1 (NQO1) is an antioxidant and detoxifying enzyme that plays an important role in drug resistance and the proliferation of several cancer cells." (PMID 36313365, 2022). "In the early stages of cancer development after PAH exposure, CYP1A1, HO-1, NQO-1, and IL-6 were identified as exposure biomarkers." (PMID 36056034, 2022). "Exposure of carcinoma cells to electrophilic molecules or overexpression of NRF2 significantly increased expression of TIGAR, in parallel to the known NRF2 target genes NQO1 and G6PD." (PMID 35163828, 2022). "NQO1-mediated changes in glycolytic flux were readily detected in A549 (lung), MiaPaCa2 (pancreatic), and HCT-116 (colon) cancer cell lines by 2H-NMR after administration of [2H7]glucose." (PMID 34439319, 2021).
cancer (continued). "As the activatable substrate of NQO1, LPC can produce a large amount of reactive oxygen species after being reduced, which exert powerful anti-tumor activity in many cancers, such as lung cancer, colon cancer and pancreatic cancer." (PMID 34790130, 2021). "Nrf2 mediates multiple antioxidant enzymes, such as glutathione S-transferase A2 (GSTA2) and NADPH quinone oxidoreductase 1 (NQO1), to protect cancer cells from oxidative stress." (PMID 34209775, 2021). "Conversely, overexpression NQO1 and GSTP1 promote cancer cell proliferation, supporting that higher NQO1 and GSTP1 levels are essential for cancer cell proliferation and the redox homeostasis." (PMID 33087132, 2020). "To further examine the effects of NQO1 and GSTP1 on U87MG/EGFRvIII cancer cell proliferation in vivo, we constructed stable knockdown cell lines that expressed their specific shRNAs." (PMID 33087132, 2020). "In this study, we found that both NQO1 and GSTP1 were overexpressed in GBM and functioned to inhibited oxidative stress and prevent cancer cell death." (PMID 33087132, 2020). "Inactivation of both NQO1 and GSTP1 with siRNA or MNPC results in imbalanced redox homeostasis, leading to apoptosis and mitigated cancer proliferation in vitro and in vivo." (PMID 33087132, 2020). "Human NQO1 [NAD(H):quinone oxidoreductase 1] is a multi-functional and stress-inducible dimeric protein involved in the antioxidant defense, the activation of cancer prodrugs and the stabilization of oncosuppressors." (PMID 32825392, 2020). "Regardless, the use of NQO1-bioactivatable agents to modulate PARP activity, NAD+ and PAR to induce cell death is a viable strategy to treat cancer." (PMID 32295316, 2020). "Another strategy to induce ROS specifically in cancer cells takes advantage of a gene that is over-expressed in many cancers, NADP quinone oxidases 1 (NQO1)." (PMID 31288436, 2019). "One such cancer-specific target enzyme is the NAD(P)H quinone oxidoreductase 1 (NQO1) and accurate detection of NQO1 activity with high sensitivity and selectivity is useful for the early diagnosis of cancer." (PMID 31189950, 2019). "Therefore, after the two-electron reduction of RH1 by NQO1 it preferentially induces DNA alkylation and cross-linking, while reduction by non-NQO1 reductases ultimately results in the generation of free radicals, oxidative stress and, consequentially, cytotoxicity in cancer cells." (PMID 31336714, 2019). "First, it should be noted that the intensity of the nuclear and cytoplasmic NQO1 signal was far less prominent in Cal 27 under NC1, than in the other two cancer cell lines." (PMID 31470592, 2019). "Some anti-cancer drugs (e.g. mitomycin C and 3-hydroxy-5-aziridinyl-1-methyl-2 (1H-indole-4,7-dione)prop-β-en-α-ol or EO9) are reductively activated by NQO1, a fact which means that their activity will be higher in cancer cells which over-express the enzyme." (PMID 30518535, 2019). "This pattern is believed to be the preferred one in anaerobic conditions and the enzyme responsible for them is NQO1 (NADPH: quinone oxidoreductase 1), which is abundantly expressed in cancer tissues." (PMID 31388334, 2019). "NAD(P)H-quinone oxidoreductase 1 (NQO1), an antioxidant/detoxifying enzyme, plays important roles in chemo-resistance and proliferation in several cancer cells." (PMID 29914576, 2018). "Here, we successfully developed a biocompatible, cell permeable and highly specific NQO1-responsive turn-on fluorescent probe (NQ-DCP) with a large Stokes shift to detect cancer cells." (PMID 30487423, 2018). "NQO1 and MRP1 are both downstream proteins of Nrf2 and play important roles in cancer chemotherapy resistance." (PMID 28427200, 2017).
cancer (continued). "Firstly, BVDU enhances the activity of NAD(P)H: quinone oxidoreductase 1 (NQO1), a FAD containing quinone reductase, which is frequently decreased in MDR cancer cells." (PMID 29137448, 2017). "In this regard, it has been observed that when cancer cells (breast TD47D) were treated with SF, NAD(P)H:quinone oxidoreductase 1 (NQO1), an activator of mitomycin C (MMC), was induced and cells were sensitized to MMC." (PMID 26950072, 2016). "Nrf2 and its target genes (e.g., heme oxygenase-1 (HO-1)], NAD(P)H:quinone oxidoreductase 1 (NQO-1), and sulfiredoxin-1 (Srx1)) protect not only normal cells but also cancer cells from oxidative stress." (PMID 26904167, 2016). "Here we revealed previously unsuspected pro-tumorigenic roles for NQO1 that essentially increase the expression of the HIF-1α protein, a central transcriptional factor of the hypoxic response of cancer cells to the hypoxic tumour microenvironment." (PMID 27966538, 2016). "Since LAT1 is the dominant transporter for tryptophan and is overexpressed in malignant tumors to support cell growth, we then focused on the study of LAT1 in response to NQO1 activation." (PMID 27566573, 2016). "Nrf2 renders cancer cells resistant to oxidative stress-mediated cell death by activating the transcription of antioxidant genes including HMOX1 and NQO1." (PMID 27764794, 2016). "NAD(P)H: quinone oxidoreductase 1 (NQO1), a flavin protease enzyme prevalent in most eukaryotic cells, has attracted considerable attention because of important roles in cancer chemoprevention and oncotherapy." (PMID 27566573, 2016). "These merged DMxDE datasets suggest some known or previously reported/suspected cancer genes [PR: SPARCL1, NQO1, CST1, MELK1, DPT, FAM83A, MMP9; GB: FOXM1, TFAP2, GREM1, ITGA8, GRIA1, SLIT3] as well as many previously unreported genes/loci." (PMID 26683690, 2015). "This property confers β-lap as well as other NQO1 targeting agents such as Tanshinone IIA a feature of high selectivity in killing cancer cells while sparing normal tissues." (PMID 25692465, 2015). "The use of β-lap with NAMPT inhibitors results in synergistic NQO1- and PARP1-dependent cancer cell death, allowing the use of lower doses and shorter treatment times for both therapeutics." (PMID 25590809, 2015). "In this study, we have investigated the involvement of NQO1 in OGD-mediated AMPK activation and cancer cell death." (PMID 25586669, 2015). "The use of ß-lap with GLS1 inhibitors results in synergistic NQO1- and PARP-dependent cancer cell death, allowing use of lower doses and shorter treatment times for both agents." (PMID 26462257, 2015). "Thus, lines of evidence seem to support the hypothesis that NQO1 plays a role in cancer prevention." (PMID 25714028, 2015). "The purpose of the present study was to investigate the involvement of NQO1 in the activation of AMPK and the suppression of mTOR in cancer cells under oxidative stress (more specifically, OGD)." (PMID 25586669, 2015). "Enzymes utilized for glutamine metabolism in PDA, GLS1, GOT1/2, and malic enzyme 1 (ME1) (see pathway), in addition to NQO1, were significantly upregulated in PDA compared to 17 other cancers when assessed using the Oncomine webtool." (PMID 26462257, 2015). "Concurrently, WA promotes NQO1-driven stabilization of TAp73, which confers synthetic lethality with JNK-related TAp73 activation in cancer cells." (PMID 25341038, 2014). "However, from the present study, we can conclude that sulindac and its metabolites increase NQO1 expression and enzyme activity, and thus are potential synergistic drugs that might be used in combination with β-lapachone to treat cancer cells with high resistance to β-lapachone cytotoxicity." (PMID 24505400, 2014).
cancer (continued). "When two cancer cell lines, CL1-1 and CL1-5, with low NQO1 expression and activity, were co-incubated with sulindac or its metabolites and β-lapachone, much higher cell death was seen with the CL1-5 cells than the CL1-1 cells." (PMID 24505400, 2014). "Despite the overwhelming evidence suggesting importance of both NQO1 and KRAS in the pathogenesis of cancers, we are aware of only a single study investigating possible associations between them." (PMID 25222473, 2014). "The anti-cancer activity of β-lap has been shown to be due to the two-electron reduction of β-lap mediated by NAD(P)H:quinone oxidoreductase (NQO1, DT-diaphorase) using NADH or NAD(P)H as electron sources." (PMID 21998736, 2011). "Dysregulation of APA is widespread in cancer; for example, the prevalent shortening of the 3'UTR in cancer cells can lead to upregulation of oncogenes (such as NQO1) or inactivation of tumor suppressor genes, thereby promoting tumor proliferation, metastasis, and metabolic abnormalities 53-55." (PMID 40384875, 2025). "We show that cancer cells react more sensitive to low- and high-LET irradiation than normal cells when treated with a combination of the glycolytic inhibitor 2-DG and the NQO1 inhibitor ES-936." (PMID 40900796, 2025). "The concept of inhibiting NQO1 activity for cancer therapy has not been attractive because of its undefined role in cell proliferation; however, it has garnered some attention." (PMID 39120303, 2024). "Despite the concerns and limitations noted, there is no doubt that NQO1 has evoked great interest encompassing the areas of tumor biology, drug discovery, chemistry, and cancer imaging and has emerged as a tumor-selective drug target." (PMID 39120303, 2024). "Also, some OE proteins are involved in TNBC cancer proliferation, such as ZA2G, CBG, SIR6, and NQO1, through different mechanisms." (PMID 39367005, 2024). "NAD(P)H: Quinone Oxidoreductase 1 (NQO1) is a flavoenzyme that can be upregulated by the transcription factor nuclear factor erythroid 2-related factor 2 (NRF2), which plays important roles in cell detoxification, cancer cell growth, and immune response." (PMID 37583897, 2023). "Therefore, further investigation of the role of NQO1 in the context of the complex relationship between the involvement of CKS1 in cell cycle progression and c-Fos in cancer cells is warranted, an investigation that we plan to undertake in the future." (PMID 36793872, 2023). "Finally, the Genomics of Drug Sensitivity in Cancer (GDSC) and Cancer Therapeutics Response Portal (CTRP) datasets were used to evaluate the impact of NQO1 expression on the response to various anticancer drugs." (PMID 37583897, 2023). "NQO1 is a ubiquitous soluble enzyme that can be upregulated by the transcription factor NRF2, which activates the expression of a variety of genes involved in protecting cells from oxidative damage and, eventually, the development of cancer." (PMID 37583897, 2023). "Next, we investigated whether NQO1-induced c-Fos regulates CKS1 expression and cell cycle progression at the G2/M phase in cancer cells." (PMID 36793872, 2023). "Overall, FRV–1 is a novel Complex I inhibitor in D-active conformation, blocking possibly the re-activation to A-state, producing selective anti-cancer effects in NQO1-negative BC cell lines." (PMID 37627592, 2023).